ENSG00000255292 (novel transcript)
Gene: Protein-coding gene on chromosome 11 (112,086,903 to 112,193,805, forward strand). Ensembl gene ENSG00000255292.
Genetic constraint (gnomAD): Missense variants: 131 observed, 150.25 expected, observed/expected ratio (o/e) 0.87, 90% interval 0.76 to 1.01. Synonymous variants: 45 observed, 54.86 expected, observed/expected ratio (o/e) 0.82, 90% interval 0.64 to 1.05.